TYR (tyrosinase)
Diseases named in the same sentence as TYR in open-access papers (continued):
Sharing a sentence is not in itself a finding about the gene and the disease.
melanoma (continued). "Tyrosinase has therefore been considered an important target for the development of therapeutic agents for pigmentation disorders and the treatment of melanoma." (PMID 40143194, 2025). "Antimelanogenic activity was assessed in α-melanocyte-stimulating hormone (α-MSH)-stimulated B16F10 melanoma cells by measuring melanin content and tyrosinase activity." (PMID 41465805, 2025). "This enzymatic activity not only contributes to skin pigmentation but also influences the behavior of melanoma cells, making tyrosinase a dual target in therapeutic strategies." (PMID 40332760, 2025). "While individualized mRNA vaccines encode for tumor- and host-specific antigens, BNT111 aims to induce expression of the four most frequent melanoma-associated antigens, NY-ESO-1, MAGE-A3, tyrosinase, and TPTE, again utilizing mRNA vaccine technology." (PMID 41012188, 2025). "Tyrosinase activity was markedly reduced in protein lysates obtained from cells treated with fisetin (20, 40 μM), both in untreated melanoma and α-MSH-stimulated melanoma cells." (PMID 41373883, 2025). "Fisetin (0–40 μM) was added to a mixture containing tyrosinase enzyme extracted from human melanoma cells and its substrate, L-DOPA." (PMID 41373883, 2025). "Tyrosinase (TYR) is a copper-containing oxidase used as a reliable biomarker for melanoma and vitiligo." (PMID 40142117, 2025). "As a result, compounds 5, 12, 13, 14 and 15 increased melanin contents and improved TYR activity in B16 melanoma cells in a concentration‐dependent manner." (PMID 40457938, 2025). "Specifically, cellular tyrosinase activity decreased by approximately 50-fold compared with untreated melanoma cells." (PMID 41373883, 2025). "The phase 2 trial BNT111-01 (NCT04526899) aims to assess the effect of a universal mRNA vaccine, BNT111, which encodes for four pre-specified proteins, NY-ESO-1, MAGE-A3, tyrosinase, and TPTE, in patients with unresectable melanoma." (PMID 41012188, 2025). "In contrast, this novel method of assessing the metabolic activation of chemicals by analyzing tyrosinase-dependent cytotoxicity in Nrf2-depleted melanoma cells is convenient and has superior sensitivity and specificity." (PMID 39858507, 2025). "In cellular models (SK-Mel-28 melanoma cells), phycocyanin demonstrated tyrosinase inhibition potential after 60 min/120 min–30.88 μg/mL/39.87 μg/mL, respectively, a result comparable to the ascorbic acid control (34.06 μg/mL/17.48 μg/mL)." (PMID 41515317, 2025). "In α-MSH-induced B16-F10 melanoma cells, 5 μM Kuraridin significantly reduced intracellular and extracellular melanin content by directly suppressing tyrosinase activity." (PMID 40076896, 2025). "In an early phase I/II trial, patients with metastatic melanoma were treated intradermally with vaccines containing six melanoma antigens (MelanA, tyrosinase, gp100, MAGEA1/3, survivin), applying RNA protection with the cationic peptide protamin." (PMID 40361349, 2025). "The relationship between tyrosinase activity and melanoma cell viability is well documented; studies indicate a correlation between increased tyrosinase activity, increased melanin content, and enhanced melanoma cell survival." (PMID 40332760, 2025). "Tyrosinase, a key enzyme in melanin biosynthesis, plays a significant role in melanoma development and progression." (PMID 40332760, 2025). "Experimental results demonstrated that maculosin inhibited intracellular melanin content and tyrosinase activity in a concentration-dependent manner in B16F10 melanoma cells." (PMID 40005169, 2025). "After administering PPV to B16F10 melanoma cells, we measured melanin content and gene expression of TYR, TRP‐1, and TRP‐2 using a microplate reader and qPCR." (PMID 41408899, 2025). "Collectively, these results demonstrate that PMMEXOs exhibit significant anti-melanogenic properties, partly through the modulation of tyrosinase activity within melanoma cells." (PMID 40747328, 2025).
melanoma (continued). "In this study, the methanol extract of Xanthium strumarium L. was identified as a potent inhibitor against tyrosinase in a cell lysate assay utilizing human MM418C1 melanoma cells." (PMID 41011583, 2025). "The use of immunohistochemical markers such as HMB-45 or tyrosinase, combined with Ki-67, can help differentiate recurrent nevi from melanoma." (PMID 41202496, 2025). "Encouraged by the strong anti-proliferation effects observed in vitro, we further explored the therapeutic potential of TYR-activated anti-cancer prodrugs on a DR-B16F10 melanoma-bearing mouse model." (PMID 40651969, 2025). "In melanoma cells (B16 murine melanoma cell line), TYR is co-expressed with TYRP1 or TYRP2 under the regulation of MITF." (PMID 41515356, 2025). "Both depigmentation—requiring specifically targeted and safe cosmetic agents—and the hyperpigmentation observed in melanoma remain key objectives in ongoing research on tyrosinase inhibitors." (PMID 41157098, 2025). "DHA, as the longest and the least saturated fatty acid, can decrease melanin production via the promotion of TYR degradation in murine melanoma cells." (PMID 39857428, 2025). "The therapeutic potential of tyrosinase inhibitors is further underscored by their ability to sensitize melanoma cells to other treatment modalities." (PMID 40332760, 2025). "The B16F10 melanoma cell line represents melanotic, high tyrosinase-expressing melanoma, mimicking classical pigmented, aggressive forms." (PMID 40732270, 2025). "In one such trial, 24 patients with relapsed, high-risk melanoma were administered a peptide vaccine composed of melanosomal antigens such as Melan-A/MART-1, MAGE-1, gp100, and tyrosinase, along with granulocyte-macrophage colony-stimulating factor (GM-CSF)." (PMID 40746887, 2025). "Both in vitro and in vivo studies have demonstrated that tyrosinase inhibitors not only suppress melanin biosynthesis but also enhance the sensitivity of melanoma cells to chemotherapy and radiotherapy, thereby improving therapeutic efficacy." (PMID 41157098, 2025). "Most importantly, tyrosinase inhibitors show promising prospects in the treatment of melanoma, an aggressive skin cancer." (PMID 41157098, 2025). "The indirect impact of fisetin on tyrosinase activity was evaluated using a cell-based assay, where equal amounts of protein extracted from fisetin-treated melanoma cells were used to catalyze the conversion of L-DOPA to dopachrome." (PMID 41373883, 2025). "The vaccine was well tolerated, and 62.5% of melanoma patients demonstrated an increase in anti-tyrosinase CD8+ T cell responses." (PMID 40725830, 2025). "In contrast, the Sk-Mel-28 human melanoma cell line represents amelanotic melanoma, with lower tyrosinase activity but retained enzymatic function, which is relevant to human melanomas characterized by low pigmentation." (PMID 40732270, 2025). "The enzymatic activity of tyrosinase extends beyond melanin production, also affecting the redox balance and oxidative stress within melanoma cells." (PMID 40332760, 2025). "As such, targeting tyrosinase presents a dual opportunity: it can potentially reduce melanin production, thereby addressing cosmetic concerns, while also impairing the growth of melanoma tumors." (PMID 40332760, 2025). "Under UVB, α-synuclein also attenuates tyrosinase activity stimulation in melanoma cells, thereby reducing melanin synthesis." (PMID 41515977, 2025). "RD and 4SCAP exhibit tyrosinase-dependent cytotoxicity in specific sources of melanocytes and melanoma cells." (PMID 39858507, 2025). "It has antioxidant, anti-inflammatory, and depigmenting properties, and it inhibits the enzyme tyrosinase, involved in melanin production, helping reduce dark spots and exhibiting antiproliferative effects against melanoma cells." (PMID 41375091, 2025). "In vitro models have shown that PPIs can reduce melanin synthesis and tyrosinase activity in melanoma cells, and zebrafish studies have confirmed dose-dependent pigment loss." (PMID 40920788, 2025).
melanoma (continued). "Overall, fisetin acts as a negative regulator of melanogenesis in human melanoma cells by lowering intracellular tyrosinase levels and inhibiting MITF expression." (PMID 41373883, 2025). "We investigated the effects of SPEF treatment (50–200 μg/mL) on melanin synthesis and intracellular tyrosinase activity in α-MSH (100 nM)-exposed B16F10 melanoma cells." (PMID 40003988, 2025). "These peptides are derived from melanoma-specific proteins involved in pigmentation and melanocytic differentiation, particularly tyrosinase, an enzyme essential in melanin biosynthesis." (PMID 40725830, 2025). "In B16F10 murine melanoma cells induced by α-melanocyte-stimulating hormone, melanin content and intracellular tyrosinase activity were determined, and melanogenesis-related protein expression and signaling pathways were analyzed by Western blotting." (PMID 40005265, 2025). "To elucidate how melanogenesis and tyrosinase activity levels are inhibited in B16BL6 melanoma cells exposed to CPEO, we conducted Western blotting." (PMID 41304724, 2025). "The B16F10 mouse melanoma cell line, characterized by high melanin production and stable tyrosinase activity, serves as a reliable in vitro model for studying melanogenesis due to its similarity to human epidermal melanocytes." (PMID 40005169, 2025). "Using the B16 F10 mouse melanoma model, this platform can non-invasively pierce the skin surface and detect TYR levels before and during anti-PD-1 antibody treatment." (PMID 40558432, 2025). "It is a prodrug converted by overexpressed tyrosinase in melanoma into an active o-quinone that suppresses tumour growth." (PMID 40732270, 2025). "Our findings indicate that, in vitro, SUCMSCs reduce melanin content and tyrosinase activity, inhibit melanoma cell viability, proliferation, migration, and invasion, and promote melanoma cell apoptosis." (PMID 39796281, 2025). "Applying vesicles derived from the stems and leaves of Huangqi wood to B16BL6 melanoma cells can significantly reduce melanin content and tyrosinase (TYR) activity, while leaf derived vesicles can inhibit the expression of melanin producing genes and enzymes." (PMID 41293219, 2025). "This complex interplay between tyrosinase activity, melanin production, and oxidative stress underscores the multifaceted role of this enzyme in melanoma pathophysiology." (PMID 40332760, 2025). "Second, anti-cancer prodrugs were activated in situ by TYR catalysis to overcome the drug resistance in the current melanoma treatment." (PMID 40651969, 2025). "Ellagic acid, a copper/iron chelator, inhibited α-melanocyte-stimulating hormone (α-MSH)-induced melanogenesis by downregulating MC1R expression and TYR activity in melanoma cells." (PMID 39970778, 2025). "EUE treatment significantly enhanced both mushroom and intracellular TYR activities in B16 melanoma cells under 1.5 mM H2O2-induced oxidative stress." (PMID 41496855, 2025). "Other researchers found that 4-S-cysteaminylphenol (4-S-CAP, a melanin-like pigment-forming tyrosinase substrate) significantly inhibited the growth of B16 melanoma cells inoculated into C57BL/6J mice." (PMID 40805258, 2025). "Our findings reveal that CPEO suppresses the serum-stimulated proliferation of B16BL6 melanoma cells and inhibits both melanin biosynthesis and tyrosinase enzymatic activity in response to α-MSH stimulation." (PMID 41304724, 2025). "The combined analysis of two melanoma studies identified four vitiligo susceptibility loci, including RALY-EIF252-ASIP-AHCY-ITCH, IRF4, TYR, and MC1R." (PMID 39817457, 2025). "It has been reported that tyrosinase overexpression can result in a high accumulation of melanin in the human body, leading to malignant melanoma and pigment spot diseases." (PMID 40722869, 2025). "This study aimed to identify the phytochemical composition in B. alba crude extracts and evaluate their biological activities, especially regarding melanin levels and tyrosinase activity in a human melanoma model." (PMID 39335872, 2024).
melanoma (continued). "The incubation of B16F10 melanoma cells with 25 μM LA significantly reduced TYR protein levels and decreased melanin synthesis, likely through the accelerated proteolytic degradation of TYR." (PMID 39796110, 2024). "TYR is markedly overexpressedin melanoma cancer cells, thus making it an important biomarker forthe diagnosis and treatment of melanoma." (PMID 38422393, 2024). "Tyrosinase was expressed in all pediatric melanoma samples, followed in frequency by TPTE (44.0%, n = 11), MAGE-A3 (12.0%, n = 3), and NY-ESO-1 (8.0%, n = 2)." (PMID 38890171, 2024). "The levels of intracellular melanin and tyrosinase activity were significantly higher in IBMX-treated melanoma cells than in the control group, with values of 125.00 ± 7.09% and 120.74 ± 1.05% of the control, respectively (p < 0.05)." (PMID 39335872, 2024). "In contrast, in G361 human melanoma cells, 95EtOH significantly reduced intracellular tyrosinase activity, consistent with the effects observed in the tyrosinase inhibitor treatment groups." (PMID 39684912, 2024). "The melanin production is inhibited by treatment with MQ-EO but also its major compositions, 1,8-cineole, α-pinene, and α-terpineol, through the downregulation of tyrosinase activity in α-MSH-exposed B16 melanoma." (PMID 38791435, 2024). "The RNA encodes four prevalent melanoma-associated antigens with high immunogenicity: NY-ESO-1, MAGE3, tyrosinase, and transmembrane phosphatase with tensin homology (TPTE)." (PMID 39696625, 2024). "In Frankel’s work relying on tyrosinase expressing-melanoma models, unsorted, CD4+ and CD8+ TCR-T cells exert cytotoxic activity against cognate target tumor cell line, both in vitro and in vivo." (PMID 38545119, 2024). "The 12MP and 6MHP vaccines target shared melanoma antigens, including both melanocytic differentiation proteins (MDPs: gp100, tyrosinase, and MART-1/MelanA) and cancer-testis antigens (CTAs: MAGE antigens and NY-ESO-1)." (PMID 38519525, 2024). "To assess tyrosinase ubiquitination in B16 melanoma cells, we employed an anti-ubiquitin antibody along with an anti-tyrosinase antibody." (PMID 38392670, 2024). "The expression of tyrosinase in these cells was indicated by a marked reduction in viability upon exposure to the anti-melanoma agent 4-S-cysteaminylphenol (4SCAP, 300 μM), while there was no reduced viability in mock-transfected cells." (PMID 39337478, 2024). "The study showed that kaempferide significantly increased the expression of genes related to the production of melanin (MC1R, MITF, TYR, TYRP1, and DCT) and the activity of the enzyme tyrosinase in the B16F10 melanoma cell line." (PMID 38398617, 2024). "The activities of melanin synthesis-associated components, tyrosinase, and TRP-1 and -2, as well as the content of melanin, are dose-dependently reduced by CJ-EO treatment in α-MSH-exposed B16F10 melanoma." (PMID 38791435, 2024). "All three compounds significantly inhibit the activity of intracellular TYR and the production of melanin in melanoma B16 cells." (PMID 39274866, 2024). "Plumbagin was found to inhibit α-MSH-induced melanin synthesis in B16F10 melanoma cells by suppressing tyrosinase activity." (PMID 38814149, 2024). "Immunofluorescence was employed to further examine co-expression patterns of α-Syn and tyrosinase in melanoma cases." (PMID 39411638, 2024). "By tracking the temporal variation in TYR levels, this study provides new opportunities for the monitoring and diagnosis of melanoma." (PMID 38667195, 2024). "The ligands were identified using UFLC-MS in combination with the comparison to the standard compounds, and their TYR inhibitory activities were tested by an enzymatic inhibition assay and the melanoma B16 cells." (PMID 39274866, 2024). "Alternatively, the use of electrochemical biomedical sensors are exemplified by Human epididymis protein 4 (HE4) in serum as biomarker for ovarian cancer, and detection of tyrosinase (TYR) enzyme as a biomarker to monitor melanomas." (PMID 38841615, 2024).
melanoma (continued). "The intracellular tyrosinase activity in IBMX-stimulated melanoma was significantly inhibited by DFRB and H, at 106.87 ± 2.32 and 105.63 ± 9.00% of the control (p < 0.05)." (PMID 38999635, 2024). "One possible mechanism involves shared antigens between melanocytes and melanoma cells, such as tyrosinase and related proteins TRP-1 and TRP-2, gp100 and Melan-A." (PMID 39125477, 2024). "Healthy subjects exhibited tyrosinase values ranging from 0.1 to 1.0 nkatal/L, while melanoma patients showed significantly higher levels ranging from 1.1 to 10.6 nkatal/L." (PMID 39766118, 2024). "Since MITF controls the expression of genes required for melanin synthesis, including tyrosinase, future elucidation of the specific effects between sulfation and melanogenesis may provide new insight into the complex biology underlying melanogenesis and melanoma." (PMID 38892038, 2024). "In particular, UPF3, which was isolated by anion-exchange chromatography, demonstrated potent anti-melanogenic effects on α-MSH-stimulated B16F10 melanoma cells by inhibiting tyrosinase signaling pathways and enzyme activity." (PMID 39408953, 2024). "In our previous study, among 20 amidated amino acids, only C-NH2 inhibited the catalytic activity of TYR in vitro and melanin synthesis in human melanoma MNT1 cells and normal human epidermal melanocytes." (PMID 38539863, 2024). "4SCAP has been reported to show tyrosinase-dependent cytotoxicity and to cause a marked decrease in cell viability in hTYR-293T and in B16BL6 melanoma cells." (PMID 39337478, 2024). "Again, adult melanomas frequently expressed tyrosinase, though slightly less so than the other melanoma cohorts (86.2%, n = 25)." (PMID 38890171, 2024). "Although marein showed a weak inhibition effect in vitro, it inhibited the intracellular tyrosinase activity and diminished melanin production in melanoma B16 cells as did the other two inhibitors." (PMID 39274866, 2024). "This study offers a novel approach for in situ TYR analysis in skin, serving as an appealing alternative to prior serum-based assays for melanoma screening and diagnosis." (PMID 38667195, 2024). "In this study, we developed a microneedle-based SERS sensor for in situ detection of TYR to facilitate rapid and effective clinical screening for melanoma." (PMID 38667195, 2024). "Regarding the melanogenesis activity, the measurement involved assessing intracellular melanin levels and tyrosinase activity in melanoma cells." (PMID 38999635, 2024). "In a recent study, the anti-tyrosinase activity of traditional Chinese medicine including rosehips has been evaluated on mushroom (ab), human (hs) and mouse melanoma B16F0 (mm) TYR." (PMID 38666029, 2024). "This dual-detection mechanism enhances the accuracy of real-time tyrosinase monitoring for melanoma detection." (PMID 40771575, 2024). "Tyrosinase, over-expressed in malignant melanoma cells, is considered as a special target that can activate the anti-melanoma prodrugs." (PMID 39128942, 2024). "The fermentation broth of DaiDai fruit exhibited inhibitory effects on tyrosinase and melanin production in mouse melanoma cells B16-F10 induced by α-MSH and anti-inflammatory properties in a zebrafish inflammation model." (PMID 39077743, 2024). "We found that all extracts and their bioactive compounds significantly inhibited melanin content and tyrosinase activity in B16 mouse melanoma cells stimulated with IBMX." (PMID 39684912, 2024). "The overexpression of tyrosinase results in the intracellular accumulation of melanin and can be observed in melanoma." (PMID 39407644, 2024). "By contrast, a later study found an association of OCA2 variations with BCC risk and also confirmed increased melanoma risk for variations in TYRP1, SLC45A2, and ASIP and increased SCC risk (squamous cell carcinoma) for TYR and ASIP." (PMID 39682251, 2024).